NFX1 (nuclear transcription factor, X-box binding 1)
Description:
Binds to the X-box motif of MHC class II genes and represses their expression. May play an important role in regulating the duration of an inflammatory response by limiting the period in which MHC class II molecules are induced by interferon-gamma. Isoform 3 binds to the X-box motif of TERT promoter and represses its expression. Together with PABPC1 or PABPC4, isoform 1 acts as a coactivator for TERT expression. Mediates E2-dependent ubiquitination.
Synonyms: NFX2; MGC20369; Tex42; TEG-42
Tractability: Antibody: its Gene Ontology location is reachable by antibodies, with high confidence. PROTAC: UniProt records ubiquitination sites on it; ubiquitination databases record sites on it; its protein half-life has been measured.
Gene: Protein-coding gene on chromosome 9 (33,290,428 to 33,371,872, forward strand). Ensembl gene ENSG00000086102.
Subcellular location: Nucleus
Subcellular location (Human Protein Atlas): Nucleoplasm; Cytosol; Nucleoli; Plasma membrane
Gene Ontology:
Molecular function: DNA-binding transcription repressor activity, RNA polymerase II-specific; protein binding; RNA binding; RNA polymerase II transcription regulatory region sequence-specific DNA binding; ubiquitin protein ligase activity; DNA-binding transcription factor activity, RNA polymerase II-specific; DNA-binding transcription factor activity; nucleic acid binding; zinc ion binding
Biological process: negative regulation of transcription by RNA polymerase II; protein autoubiquitination; inflammatory response; protein ubiquitination; transcription by RNA polymerase II
Cellular component: nucleolus; nucleoplasm; chromatin; nucleus
Genetic constraint (gnomAD): Loss-of-function variants: 54 observed, 118.05 expected, observed/expected ratio (o/e) 0.46, 90% interval 0.37 to 0.57. The upper end of that interval is the gene's LOEUF score, 0.57, which puts it in group 2 of 6, group 1 being the genes least tolerant of losing a copy. Missense variants: 1,056 observed, 1,317.5 expected, observed/expected ratio (o/e) 0.8, 90% interval 0.76 to 0.84. Synonymous variants: 445 observed, 459.55 expected, observed/expected ratio (o/e) 0.97, 90% interval 0.89 to 1.05.
Homologues: Orthologues: chimpanzee NFX1 (100% identical), macaque NFX1 (98% identical), dog NFX1 (93% identical), pig NFX1 (92% identical), guinea pig NFX1 (91% identical), mouse Nfx1 (88% identical), rabbit NFX1 (87% identical), rat Nfx1 (85% identical), tropical clawed frog nfx1 (60% identical), zebrafish nfx1 (51% identical), Drosophila melanogaster stc (32% identical), Caenorhabditis elegans nfx-1 (31% identical). Paralogues in human: NFXL1 (23% identical).
Diseases named in the same sentence as NFX1 in open-access papers:
NFX1 is named in the same sentence as 21 diseases in open-access papers, as found by Europe PMC text mining. Sharing a sentence is not in itself a finding about the gene and the disease. The quoted sentences say what the papers report.
cervical cancer (7 papers, 2021 to 2025). A primary or metastatic malignant neoplasm involving the cervix. "Several of these differentially expressed genes highlight how NFX1-123 depletion disrupts essential mechanisms that are relevant to cervical cancer cell survival and virus-associated pathways." (PMID 40563693, 2025). "The longer splice variant, NFX1-123, is highly expressed in cervical cancers and cell lines and is upregulated in HPV+ compared to HPV- head and neck primary tumors." (PMID 34944802, 2021). "In this study, we sought to better understand the role of NFX1-123 using an scRNAseq analysis of cervical cancer cell lines." (PMID 40563693, 2025). "A reduction of NFX1-123 in cervical cancer cell lines leads to decreased hTERT and a slowing of cell growth." (PMID 40563693, 2025). "In cervical cancer cell lines, pharmacological inhibition and reduction of NFX1-123 result in decreased cancer cell growth, survival, migration, and invasion, as well as enhanced cisplatin cytotoxic effects." (PMID 40563693, 2025). "Further, our results showed the telomerase activity regulation associated with NFX1-123 and HPV16E6 in cervical cancer." (PMID 40563693, 2025). "Not only did 16E6 bind NFX1 gene products, but we have determined that NFX1-123 expression is increased in cervical dysplasia samples and is highly expressed in cervical cancers and cervical cancer cell lines." (PMID 35891463, 2022). "NFX1, through the NFX1-91 and NFX1-123 splice variants, appears to play a critical role in driving HPV-associated cancers, with cervical cancer being the primary one studied to-date." (PMID 33808060, 2021). "In conclusion, our findings using in silico analyses and in vitro model systems of HPV+ dysplasias and cancers uncovered gene alterations correlated with cervical cancer progression and regulated by NFX1-123 and HPV16 E6 and E7." (PMID 34944802, 2021). "These analyses show the dynamic differences in 16E6/NFX1-123 co-regulated genes at different stages of cervical cancer progression." (PMID 34944802, 2021). "Additionally, in The Cancer Genome Atlas cervical cancer data set, 13.2% of genes correlated with NFX1 expression; among those correlative genes, there was significant enrichment for those associated with protein binding and RNA binding." (PMID 35891463, 2022). "To identify genes whose expression correlated with NFX1 in cervical cancers, we ranked genes based on the extent to which their expression significantly correlated with NFX1 expression in the Cancer Genome Atlas (TCGA) cervical cancer data set." (PMID 34944802, 2021). "When considering the typical progression of cervical cancer—from infection, to dysplasia, to different stages of cancer itself—it is critical to define whether the expression pattern of this subset of 16E6/NFX1-123-regulated genes can be predictive of disease progression." (PMID 34944802, 2021). "When NFX1-123 expression is decreased, pharmacologically or by CRISPR-Cas9 knock out, cervical cancer cell lines have decreased growth, survival, migration, and wound healing, as well as an enhanced cytotoxic efficacy of cisplatin, a widely used chemotherapeutic drug." (PMID 40563693, 2025). "While it is known that NFX1-123 regulates hTERT and telomerase activity in cooperation with 16E6 and PABPCs in HFK models, its exclusive function in gene expression regulation and telomerase activity have not been objectively investigated in cervical cancer models." (PMID 40563693, 2025).
breast carcinoma (1 paper, 2023). "For instance, the phosphorylated nuclear transcription factor X box binding 1 (NFX1) can be captured only in the exosomes of breast cancer patients, which may suggest that the functions of phosphorylated NFX1 are mediated under specific conditions." (PMID 36681849, 2023).
colorectal adenocarcinoma (1 paper, 2025). The most common type of colorectal carcinoma. "Similarly, NFX1 shows recurrent missense alterations in cutaneous melanoma (SKCM), while RNF10 is frequently mutated in colorectal adenocarcinoma (COAD), highlighting distinct mutation hotspots that may alter protein function in a context-dependent manner." (PMID 40591126, 2025).
dental caries (1 paper, 2021). The decay of a tooth, in which it becomes softened, discolored, and/or porous. "Those genes; NFX1 and REL could contribute to dental caries by influencing host susceptibility to oral microorganism." (PMID 34311721, 2021).
head and neck cancer (1 paper, 2021). A primary or metastatic malignant neoplasm affecting the head and neck. "We also highlight the roles NFX1 has in human disease and in cancer, with a strong focus on its collaborative role with high-risk human papillomavirus infections that cause cervical and head and neck cancers." (PMID 33808060, 2021).
Insulin resistance (1 paper, 2015). Increased resistance towards insulin, that is, diminished effectiveness of insulin in reducing blood glucose levels. "Our data demonstrated significant increases in the expression levels of several lipid metabolism-related genes, including IFNGR2 and NFX1, which modulate lipid metabolism to promote insulin resistance." (PMID 26089598, 2015).
preeclampsia (1 paper, 2015). Preeclampsia is a hypertensive disorder of pregnancy that is characterized by new-onset hypertension with proteinuria presenting after 20 weeks of gestation, and depending on mild or severe forms may initially present with severe headache, visual disturbances, and hyperreflexia. "The amount of insulin resistance genes (IFNGR2 and NFX1) may correlate with the preeclampsia syndrome, which is regarded as a key feature of preeclampsia genesis." (PMID 26089598, 2015).
viral infection (1 paper, 2017). "16E6 and NFX1-123 inhibiting immune signaling has implications not only for whether a viral infection is eliminated, but also whether a malignant growth is detected and cleared." (PMID 29117186, 2017).
cancer (7 papers, 2018 to 2025). A tumor composed of atypical neoplastic, often pleomorphic cells that invade other tissues. "Several genetic variants had high mutation rates across the entire study group in comparison with normal ovarian controls, e.g. recurrent deleterious variants in the CHD1L, GFM1, MEIS1 and NFX1 genes, suggesting specificity to cancer." (PMID 30416686, 2018). "The longer splice variant of nuclear transcription factor, X-box binding 1 (NFX1-123) is a cytoplasmic protein that has been recently reported as highly expressed in multiple cancers, including human papillomavirus (HPV)-associated cancers of the cervix and head and neck." (PMID 40563693, 2025). "Finally, we stress the emerging roles of these NFX1 splice variants in high-risk human papillomavirus-associated cancers, and the increased expression of the longer splice variant, NFX1-123, found in these cancers." (PMID 33808060, 2021). "By proxy, this demonstrates an association between NFX1-123 expression, HPV oncogenes including E6, and critical pathways that require virus–host interactions in cancer." (PMID 40563693, 2025). "Together, these findings highlight the importance of NFX1-123 in maintaining normal expression patterns that are critical for cancer cell function and behavior and highlight the diverse cellular processes it influences." (PMID 40563693, 2025). "Particularly, the genes that showed the highest mutation frequency across all cancers overall were TAF1, NFX1, and RNF10." (PMID 40591126, 2025). "NFX1, and specifically the NFX1-123 isoform, is expressed at high levels in cancers when compared to normal tissues." (PMID 33808060, 2021). "Further detailed mechanistic studies in drug resistance and stress tolerance are warranted to determine the specific functional significance of NFX1-123 in cancer development and cancer treatment outcomes." (PMID 33808060, 2021). "While this is clearly linked with two cancers that are HPV-associated (cervical and HNSCC), changes in NFX1 expression can occur in other types of cancers." (PMID 33808060, 2021). "In this review, we will summarize the data to-date on: the biologic role of NFX1 and its homologs across different species and in humans; the role NFX1 and its homologs has in disease; and the role NFX1 has in cancers." (PMID 33808060, 2021). "It is important to note as well that NFX1, and its homologs, disrupt drug interactions, affect growth, and protect against cellular and organismal stress—all functions often involved in cancer development and therapeutic resistance." (PMID 33808060, 2021). "All of these—nucleic acid binding, gene expression changes, and cellular pathway regulation—are important to understand the role NFX1 plays in cellular and organismal biology, in disease, and cancer." (PMID 33808060, 2021). "However, it is important to expand our scope to understand how narrowly or broadly NFX1-123 and PABPCs affect post-transcriptional gene regulation in the HPV life cycle and in HPV-associated cancer development and progression." (PMID 35891463, 2022). "With that, it is interesting to consider that NFX1-123 may play a more universal role in oncogenesis, and HPV co-opts that functionality, specifically manipulating it during HPV-driven cancers." (PMID 33808060, 2021).
infection (3 papers, 2021 to 2025). The state of being infected such as from the introduction of a foreign agent such as serum, vaccine, antigenic substance or organism. "Among them, the NFX1 protein was found to encode a repressor of gene expression, suggesting that NFX1 limits the immune response following infection." (PMID 39273703, 2024). "Given the similarity in NFX1-type zinc fingers between NFX1 and ZNFX1, it is plausible that zinc finger regions of ZNFX1 could mediate host RNA expression following an infection." (PMID 40170857, 2025).
tumor (3 papers, 2018 to 2024). "Four recurrent deleterious variants corresponding to the CHD1L (99.0%), GFM1 (91.7%), MEIS1 (90.6%) and NFX1 (93.8%) genes were found in the majority of the tumor samples in the study cohort, but in none of the normal controls." (PMID 30416686, 2018).
NFX1 also shares sentences with these, for which no sentence is quoted: cerebrovascular disorder (1 paper); cervical dysplasia (1); cholangiocarcinoma (1); CNS lymphomas (1); cutaneous melanoma (1); Esophageal atresia (1); human papillomavirus infections (1); intracranial aneurysms (1); malignant peripheral nerve sheath tumor (1); uterine carcinosarcoma (1).